GPR87 (G protein-coupled receptor 87)
Description:
Receptor for lysophosphatidic acid (LPA). Promotes the Hippo-YAP signaling pathway and thereby modulates glycolysis and oxidative stress production by the regulation of hexokinase-2/HK2.
Synonyms: GPR95; FKSG78; KPG_002
Tractability: Small molecule: it belongs to a druggable protein family. Antibody: UniProt places it where antibodies can reach, with medium confidence; UniProt predicts a signal peptide or a membrane-spanning region; its Gene Ontology location is reachable by antibodies, with medium confidence. PROTAC: ubiquitination databases record sites on it.
Target class: Family A G protein-coupled receptor; Membrane receptor
Gene: Protein-coding gene on chromosome 3 (151,294,086 to 151,316,820, reverse strand). Ensembl gene ENSG00000138271.
Subcellular location: Cell membrane
Subcellular location (Human Protein Atlas): Lipid droplets; Mitochondria; Nucleoplasm
Gene Ontology:
Molecular function: G protein-coupled purinergic nucleotide receptor activity; protein binding; G protein-coupled receptor activity
Biological process: G protein-coupled receptor signaling pathway; G protein-coupled purinergic nucleotide receptor signaling pathway
Cellular component: plasma membrane; membrane
Genetic constraint (gnomAD): Loss-of-function variants: 15 observed, 13.98 expected, observed/expected ratio (o/e) 1.07, 90% interval 0.72 to 1.63. The upper end of that interval is the gene's LOEUF score, 1.63, which puts it in group 6 of 6, group 1 being the genes least tolerant of losing a copy. Missense variants: 424 observed, 440.27 expected, observed/expected ratio (o/e) 0.96, 90% interval 0.89 to 1.04. Synonymous variants: 162 observed, 161.23 expected, observed/expected ratio (o/e) 1, 90% interval 0.88 to 1.14.
Homologues: Orthologues: chimpanzee GPR87 (99% identical), macaque GPR87 (99% identical), dog GPR87 (94% identical), guinea pig GPR87 (92% identical), mouse Gpr87 (91% identical), pig GPR87 (91% identical), rat Gpr87 (91% identical), tropical clawed frog gpr87 (65% identical). Paralogues in human: P2RY14 (42% identical), P2RY12 (37% identical), P2RY13 (35% identical), GPR34 (24% identical), GPR171 (23% identical), PTAFR (22% identical).
Diseases named in the same sentence as GPR87 in open-access papers:
GPR87 is named in the same sentence as 24 diseases in open-access papers, as found by Europe PMC text mining. Sharing a sentence is not in itself a finding about the gene and the disease. The quoted sentences say what the papers report.
pancreatic cancer (11 papers, 2017 to 2025). "Previous studies have reported that GPR87 overexpression promotes invasiveness of liver and pancreatic cancer cells, whereas loss of GPR87 inhibits invasive ability in pancreatic cancer cells." (PMID 35008182, 2021). "For instance, GPR87 plays a critical oncogenic role in pancreatic cancer progression, and SH3GL3 is a novel invasion-associated candidate gene that likely contributes to the invasive genotype of malignant gliomas." (PMID 32411243, 2020). "Ninety-six human pancreatic cancer tissue samples were analyzed by immunochemistry (IHC) to investigate the association between GPR87 expression and the clinicopathological characteristics of pancreatic cancer." (PMID 28288630, 2017). "Collectively, these findings suggest a potential association between GPR87 upregulation and progression of pancreatic cancer." (PMID 28288630, 2017). "Herein, our study showed that GPR87 was overexpressed in pancreatic cancer and associated with poor survival of pancreatic cancer patients." (PMID 28288630, 2017). "Concordant with previous reports, our study showed that GPR87, a member of the GPCRs, could activate NF-κB signaling pathway in pancreatic cancer cells and that GPR87 levels were significantly associated with NF-κB activity in clinical pancreatic cancer tissues." (PMID 28288630, 2017). "Recent studies have confirmed that GPR87 is overexpressed in several malignancies such as pancreatic cancer, lung cancer and bladder cancer." (PMID 40963862, 2025). "Expressions of GPR87 are significantly upregulated in pancreatic cancer and clinical tissues, and activation of the NF-κB signaling pathway promotes pancreatic cancer metastasis." (PMID 37396042, 2023). "In pancreatic cancer, GPR87 enhances aggressiveness by activating the NF-κB signaling pathway and stem cell expansion via activation of the JAK2/STAT3 signaling pathway." (PMID 35008182, 2021). "Together, these data indicate that downregulation of GPR87 expression inhibits pancreatic cancer aggressiveness in vitro." (PMID 28288630, 2017). "IHC analysis revealed that GPR87 was significantly upregulated in pancreatic cancer and correlated with clinical features and a poor prognosis of pancreatic cancer patients." (PMID 28288630, 2017). "Collectively, our findings emphasize the role of oncogenic GPR87 in pancreatic cancer progression in vivo." (PMID 28288630, 2017). "In the present study, we provided evidence for a novel link between GPR87 and the oncogenic NF-κB signaling pathway in pancreatic cancer." (PMID 28288630, 2017). ", we found that GPR87 expression was significantly upregulated in primary pancreatic cancer tissues compared with normal pancreatic tissue." (PMID 28288630, 2017). "GPR87 is overexpressed in various cancers, including pancreatic cancer cells and tissues, and its overexpression correlates with shorter OS." (PMID 28927421, 2017). "Herein, we reported that GPR87 expression was significantly upregulated in pancreatic cancer and clinical tissues, and was correlated with the clinical features of pancreatic cancer." (PMID 28288630, 2017). "Our findings suggest that GPR87 plays a vital oncogenic role in pancreatic cancer progression and highlight its potential as a target for pancreatic cancer therapy." (PMID 28288630, 2017). "Overexpression of GPR87 promotes proliferation, metastasis, angiogenesis and resistance to apoptosis induced by a chemotherapeutic agent in pancreatic cancer." (PMID 28288630, 2017). "Taken together, these results suggest that GPR87 overexpression promotes the aggressiveness of pancreatic cancer cells in vitro." (PMID 28288630, 2017). "Our findings suggest that GPR87 plays a critical oncogenic role in pancreatic cancer progression and highlight its potential as a target for pancreatic cancer therapy." (PMID 28288630, 2017).
pancreatic cancer (continued). "Herein, we found that GPR87 was upregulated in pancreatic cancer and GPR87 overexpression promoted pancreatic tumor progression both in vivo and in vivo, which is in agreement with the oncogenic effects of GPR87 family members." (PMID 28288630, 2017). "Kaplan-Meier survival analysis of data from TCGA revealed that pancreatic cancer patients with higher expression of GPR87 had shorter overall survival." (PMID 28288630, 2017). "Downregulation of GPR87 significantly inhibited proliferation of pancreatic cells, as shown nearly 2- to 2.5-fold decreased colonies and up to 2.5- to 5-fold reduced BrdU-positive cells in GPR87-silenced pancreatic cancer cells compared to control cells." (PMID 28288630, 2017). "Herein, we reported that GPR87 was markedly overexpressed in pancreatic cancer cells and clinical tissues." (PMID 28288630, 2017). "Pancreatic cancer patients with higher levels of GPR87 expression had shorter overall survival compared to patients with lower GPR87 levels." (PMID 28288630, 2017). "In summary, we reported that GPR87 expression was significantly upregulated in pancreatic cancer, and higher GPR87 correlated with shorter overall survival of patients with pancreatic cancer." (PMID 28288630, 2017). "We found that the anchorage-independent growth ability of GPR87-overexpressing pancreatic cancer cells dramatically augmented up to 2 folds compared to control cells." (PMID 28288630, 2017). "The clinical significance and biological role of GPR87 in pancreatic cancer, however, remain to be established." (PMID 28288630, 2017). "GPR87 expression in pancreatic cancer cell lines, paired patient tissues were determined using western blotting and Real-time PCR." (PMID 28288630, 2017). "Western Blot and real-time PCR was performed and showed that GPR87 expression was upregulated in the six pancreatic cancer cell lines compared with normal human pancreatic ductal epithelial cells (HPDECs)." (PMID 28288630, 2017). "GPR87 was significantly upregulated in pancreatic tumors compared with matched adjacent normal pancreatic tissues." (PMID 28288630, 2017). "Interestingly, it is worth noting that GPR87 is generally considered as a tumor driver in the tumorigenesis of pancreatic cancer, lung cancer, bladder cancer, and liver cancer." (PMID 34595101, 2021). "To further determine the clinical correlation between GPR87 and NF-κB signaling pathway, we examined whether GPR87 induced p65 nuclear accumulation in pancreatic cancer and elevated expression of NF-κB downstream genes in clinical samples." (PMID 28288630, 2017). "Moreover, overexpression of GPR87 also increased the resistance of pancreatic cancer cells to apoptosis induced by chemotherapeutic agents gemcitabine." (PMID 28288630, 2017). "Finally, we demonstrated that GPR87 enhanced pancreatic cancer aggressiveness by activating NF-κB signaling pathway." (PMID 28288630, 2017). "According to TCGA, we found amplification of GPR87 in 25 of 184 cases, suggesting that amplification might account for GPR87 overexpression in 13.59% of pancreatic cancer patients." (PMID 28288630, 2017). "Functional assays, such as anchorage-independent growth, chicken chorioallantoic membrane (CAM) assay, transwell matrix penetration assay, and Annexin V-FITC and PI staining and a xenograft tumor model were used to determine the oncogenic role of GPR87 in human pancreatic cancer progression." (PMID 28288630, 2017). "Thus, it would be of great interest to further investigate whether upregulation of GPR87 in pancreatic cancer is attributed to STAT3-mediated transcriptional upregulation." (PMID 28288630, 2017). "Furthermore, HUVEC tube formation and CAM assays showed the abilities of pancreatic cancer cells to induce HUVEC tube formation and CAM neovascularization were inhibited in response to GPR87 knockdown." (PMID 28288630, 2017).
pancreatic cancer (continued). "Furthermore, GPR87 levels were correlated with clinical stage (p = 0.022), and TNM classification (T: p = 0.003, N: p = 0.001, M: p < 0.001) in patients with pancreatic cancer." (PMID 28288630, 2017). "Furthermore, we also found that overexpressing GPR87 or silencing GPR87 only resulted in slightly change of apoptotic rate of pancreatic cancer cells without any treatment." (PMID 28288630, 2017).
lung carcinoma (10 papers, 2006 to 2025). "We concluded that increased GPR87 expression caused by H3F3A overexpression promotes the invasion ability of lung cancer cells." (PMID 27694942, 2016). "H3F3A and GPR87 expression levels, either alone or in combination, are associated with lung cancer patients’ prognoses and have potential for the development of treatments involving GPR87 antagonists." (PMID 27694942, 2016). "Examples include MYCN upregulation (seen in H3.3-G34R in GBM and potentially impacted by H3.1 imbalance), silencing of tumour suppressors like p16 by H3.3-K27M and activation of oncogenic pathways such as GPR87 by H3.3 in lung cancer." (PMID 40987316, 2025). "According to a recently published paper, humanized anti-GPR87 mAb had anti-tumor effects in a mouse model of lung cancer." (PMID 35008182, 2021). "Conversely, inhibition of GPR87 in lung cancer suppresses tumor proliferation by reducing the expression of KRAS and c-MYC." (PMID 35008182, 2021). "Western blot analysis confirmed that LPA treatment significantly increased AKT and endothelial nitric oxide (eNOS) phosphorylation, and GPR87 overexpression further increased the effect of LPA treatment in A549 lung cancer cells." (PMID 35008182, 2021). "Alternatively, inhibition of GPR87 suppresses the migration and proliferation of lung cancer 35 Moreover, GPR87 is overexpressed in hepatocellular carcinoma, which upregulates CD133 expression and increases cancer stem cell migration and invasion." (PMID 33033514, 2020). "Our current study effectively confirms the differential mRNA expression of GPR87 and goes on to demonstrate that protein expression was also higher in a large set of lung cancer samples." (PMID 29371917, 2017). "Our results reveal a novel upstream GPR87 regulator and elucidate an important transcriptional regulation mechanism in the context of lung cancer." (PMID 27694942, 2016). "Based on previous results, the transcriptional regulation of GPR87 by H3F3A appears to be essential for the invasion ability of lung cancer cells." (PMID 27694942, 2016). "We demonstrate that GPR87 expression is upregulated by H3F3A overexpression and that H3.3 (expressed from H3F3A) is deposited at a specific intronic region of GPR87 in lung cancer." (PMID 27694942, 2016). "Similar to H3F3A, GPR87 knockdown significantly decreased lung cancer cell invasion (P=1.5 × 10−3, t-test) and MMP9 expression (P=9.5 × 10−3, t-test), but did not affect proliferation ability." (PMID 27694942, 2016). "Consequently, the researchers concluded that the combination of H3F3A and GPR87 promotes lung cancer progression and migration." (PMID 40987316, 2025). "GPR87 was suggested to contribute to the viability of human tumor cells and overexpression of GPR87 mRNA was detected in a number of malignant tumors, including lung cancer." (PMID 34112093, 2021). "Therefore, we suggest that GPR87 expression changes driven by H3F3A overexpression promote lung cancer progression." (PMID 27694942, 2016). "Thus, we suggest that the combination of H3F3A/GPR87 expression is a novel prognosis marker for early-stage lung cancer." (PMID 27694942, 2016). "As we expected that H3F3A would promote lung cancer cell invasion through GPR87, we examined whether the increased invasion ability stimulated by H3F3A overexpression could be mitigated by GPR87 knockdown." (PMID 27694942, 2016). "The expression levels of H3F3A and GPR87, either alone or in combination, are robust prognostic markers for early-stage lung cancer, and may indicate potential for the development of treatments involving GPR87 antagonists." (PMID 27694942, 2016). "Role of G protein coupled receptors are well documented in lung cancer and GPR87 could be an important gene in cancer progression." (PMID 17217525, 2006). "Therefore, targeting GPR87 in H3F3A-overexpressing lung cancer patients might be a viable strategy for post-operative adjuvant therapy." (PMID 27694942, 2016).
lung carcinoma (continued). "A number of the markers in this study had previously been reported as expressed as mRNA or protein in lung cancer: CAIX, CAXII, KK-LC-1, desmoglein 3, GPR87, Ly6/PLAUR domain-containing protein 3 and solute carrier family 7 member 11 protein." (PMID 29371917, 2017). "Five of these markers, CXorf61, DSG3, FAT2, GPR87, and LYPD3, were selected based primarily on their high and broad expression among the lung cancer samples relative to normal lung." (PMID 29371917, 2017). "EBV is a ubiquitous gamma herpesvirus that causes persistent infections and some lymphoid and epithelial tumors and might use G protein-coupled receptor (GPCR) signaling, like GPR87, a common overregulated DEG in lung cancer." (PMID 39228892, 2024). "GPR87 is upregulated in various cancers, but its biological function has not yet been established in lung cancer." (PMID 35008182, 2021). "Similar to GPR87 knockdown, treatment with Ki16425 significantly decreased the invasion ability of A549 lung cancer cells, whereas it did not significantly affect proliferation ability." (PMID 27694942, 2016).
bladder cancer (7 papers, 2013 to 2025). "The aim of the present study is to examine the effect of silencing GPR87 expression with a replication-deficient recombinant adenoviral vector expressing short hairpin RNA targeting GPR87 (Ad-shGPR87) and to explore the underlying molecular mechanisms in bladder cancer cells." (PMID 26473854, 2015). "GPR87 promotes cell proliferation in human bladder cancer cells, as well as growth and metastasis of CD133+ cancer stem-like cells in hepatocellular carcinoma." (PMID 32547950, 2020). "GPR87 appeared to be a promising target for gene therapy, and Ad-shGPR87 had strong antitumor effects, specifically anti-proliferative and pro-apoptotic effects, against GPR87-expressing human bladder cancer cells." (PMID 26473854, 2015). "The adenoviral vector expressing shRNA for silencing the expression of GPR87 effectively inhibited cell proliferation and induced apoptosis in GPR87-expressing bladder cancer cells." (PMID 26473854, 2015). "In the present study, we further explored the antitumor activity in more bladder tumor cell lines both in vitro and in vivo and aim to clarify the functional role of GPR87 in bladder cancer." (PMID 26473854, 2015). "Six GPR87-expressing human bladder cancer cells, HT1197, HT1376, J82, RT112, TCCSUP and UMUC3, were used." (PMID 26473854, 2015). "The overexpression of GPR87 has also been reported in many malignant tumors including bladder cancer." (PMID 26473854, 2015). "The relative GPR87 gene expression level referred to the internal control was evaluated in eight human bladder cancer cell lines." (PMID 26473854, 2015). "Here we demonstrated both in vitro and in vivo that GPR87 contributes to the viability of human bladder cancer cells." (PMID 26473854, 2015). "With this effective tool, we then analyzed the intracellular pathways to uncover the mechanism by which GPR87 is able to regulate the proliferation and survival of human bladder cancer cells." (PMID 26473854, 2015). "Protein expression levels of GPR87 in surgical bladder cancer specimens were also immunohistochemically analyzed, and special attention was paid to cell proliferation, including tumor grade and Ki-67 index." (PMID 23752273, 2013). "In the present study, we measured GPR87 mRNA expression levels in several bladder cancer cell lines and investigated the influence of silencing GPR87 mRNA on cell proliferation." (PMID 23752273, 2013). "Further investigation to clarify the clinical importance of GPR87 as a predictive marker and a therapeutic target for bladder cancers is warranted." (PMID 23752273, 2013). "GPR87 may be a very good candidate target when developing new treatment strategies for patients with bladder cancer." (PMID 26473854, 2015). "GPR87 expression was assessed in seven human bladder cancer cell lines." (PMID 23752273, 2013). "In addition, GPR87 was overexpressed in some bladder cancer tissues and adenocarcinoma of the lung." (PMID 23752273, 2013). "Although GPR87 was reported to be overexpressed in squamous cell carcinomas in different locations and in their lymph node metastases, including bladder cancer tissue, bladder cancer cell lines have not been adequately studied." (PMID 26473854, 2015).
hepatocellular carcinoma (6 papers, 2013 to 2025). A malignant tumor that arises from hepatocytes. "Recent studies have revealed that GPR87 plays a key role in modulating the expression of CD133 and contributes to the growth and metastasis of hepatocellular carcinoma (HCC) cells." (PMID 40207812, 2025).